IL6 (interleukin 6)
Diseases named in the same sentence as IL6 in open-access papers (continued):
Sharing a sentence is not in itself a finding about the gene and the disease.
tumor (continued). "The revamping of immunity support for better tumor control by targeting IL-6/STAT3 signaling in EOC." (PMID 31861720, 2019). "We studied IL-6 and IL-8 function in primary oesophageal squamous carcinoma and NK cell co-cultures in vitro and by a xenograft tumour model in vivo." (PMID 31324197, 2019). "The number of M2 macrophages is increased due to chemokines released from tumor cells: Il-6, IL-4, VEGF, TGF-β." (PMID 30680411, 2019). "For instance, MMPs and IL6 secreted by senescent fibroblasts have been shown to contribute to a tumor‐promoting microenvironment in the breast and prostate and tumor progression (Liu & Hornsby, 2007; Tsai, Chuang, Little, & Yuan, 2005)." (PMID 31389184, 2019). "To aid in grouping and selecting tumors and tumor regions suitable for RNA-seq analysis, we first stratified animals on the basis of serum IL-6 and serum CINC-1." (PMID 31428571, 2019). "IL-6 has multiple effects on tumour progression, of which some are the result of direct action on tumour cells, while others are the result of its activity on other cells in the tumour microenvironment." (PMID 31010082, 2019). "IL-6R expression has been reported in NPC and IL-6 is produced by tumor cells in the TME, acting as a growth factor and resulting in STAT3 activation." (PMID 29652813, 2018). "The results showed that IL-3, IL-6, and IL-10 were differentially expressed in splenocytes from tumor bearing WT mice compared with tumor-bearing IRF-8−/−, naïve WT and naïve IRF-8−/− mice." (PMID 29438283, 2018). "PTPRD has been characterized as a tumor suppressor gene in MM and a homozygous deletion in PTPRD encoding locus is known to modulate phosphorylation of STAT3 that promotes IL6 signaling." (PMID 30134812, 2018). "Studies with IKKβ, TRAF2 and PERK knockout sub-lines of 786-O cells demonstrated that activation of both NF-κB and PERK was essential for sunitinib-induced production of IL-6 and IL-8 in tumor cells." (PMID 29515108, 2018). "TAMs induce EMT of tumor cells by secreting factors such as interleukelin-6 (IL-6), interleukelin-8 (IL-8), tumor necrosis factorα (TNFα), TGFβ, EGF, VEGF, matrix metalloproteinase-2 (MMP-2) and MMP-9." (PMID 30157906, 2018). "The reduction in TAM migration into the tumors resulted in decreased IL-6 signaling and delayed tumor growth and skin invasion." (PMID 29862083, 2018). "MiRNA binds the TLR8 receptor of the immune cells, inducing more IL-6 and other cytokines as well as increasing invasion of the tumor cells in vitro." (PMID 30038723, 2018). "In the xenograft tumor model, the tumor growth of MCF10DCIS.com was enhanced by the co-injection of preadipocytes, and the administration of IL-6 neutralizing antibodies resulted in potent effects on tumor inhibition." (PMID 30134951, 2018). "In particular, the persistent stimulation of IL-6 causes the activation of JAK2 and the subsequent phosphorylation/activation of STAT3, which contributes to tumor growth, chemo-resistance and metastasis." (PMID 29651140, 2018). "The pro-inflammatory cytokines, i.e. tumor necrosis factor-α (TNF-α), interleukin-1β (IL-1β), and IL-6, activate inflammation, as proposed for the deterioration of angiogenesis in tumor cells." (PMID 30479366, 2018). "There was additional focus with respect to their potential autocrine activity, on quantifying cytokine receptors described to play a role in metastasis and tumor formation, i.e. IL-6/IL-8." (PMID 29941048, 2018). "The mTOR inhibitor, rapamycin, results in direct inhibition of IL-1α synthesis (and consequently IL-6 secretion) which successfully prevented the tumor-promoting effects of senescent fibroblasts." (PMID 29868482, 2018). "IL-6 is tumorigenic, promotes tumor cell invasion, and serum levels of IL-6 correlate with worse prognosis in CRC." (PMID 29462209, 2018).
tumor (continued). "Canonical NF-κB also modifies the tumor microenvironment by inducing the secretion of proinflammatory cytokines such as IL-6, resulting in the activation of its responsive transcription factor STAT3 in K-Ras-mutant lung tumors." (PMID 29601548, 2018). "IL-6 and M-CSF, cytokines secreted by tumor cells, have been shown to switch the differentiation of CD34+ progenitors from DCs to CD14+ monocytes that failed to mediate allogeneic T cell proliferation." (PMID 30619378, 2018). "These oncological stimulatory effects were suggested to result from the proinflammatory response towards peritoneal infection, facilitating tumor recurrence through secretion of multiple tumor stimulatory factors including IL-6 and VEGF." (PMID 30176921, 2018). "We have reported that IL-6 derived from tumor-resident mesenchymal stem cells induces neutrophil activation, resulting in enhanced angiogenesis and tumor metastasis." (PMID 30292233, 2018). "In conclusion our result showed that PD‐L1 (CD274) expression in tumor cells is associated with chemoresistance and the poor prognosis of HNSCC through IL‐6." (PMID 29761938, 2018). "Δ122/+ IL-6+/− and Δ122/+ IL-6−/− mice had significantly reduced tumour incidence compared to Δ122/+ IL-6+/+ mice (p = 0.01 and 0.015, respectively, χ2-test)." (PMID 29343721, 2018). "Tumor-derived IL-6 impaired the differentiation of myeloid cells and promoted the accumulation of e-MDSCs by inhibiting SOCS3 expression and persistently activating the JAK/STAT signaling pathway." (PMID 30083161, 2018). "For instance, the induction of interleukin-6 (IL-6), IL-10, and colony stimulating factor 1 (CSF-1) contributes to the proliferation and invasion of tumor cells and thereby displays a pro-tumorigenic role." (PMID 30115069, 2018). "Systemic administration of IL-6 in the CCA murine model induced tumor development at a similar rate to IL-33." (PMID 30205617, 2018). "Skeletal muscles of C26 tumor-bearing mice were used to elucidate the connection between the elevated IL6/STAT3 signaling, cancer cachexia, and muscle wasting." (PMID 30072615, 2018). "In GI cancers, the activation level of STAT3 seems to be of importance with regard to increasing tumor size and proliferation in mouse models, and IL-6 seems to be the most important activator of the STAT3-cascade." (PMID 30038723, 2018). "Murine serum concentrations of the tumor-supporting cytokines Interleukin-6 (IL-6), Vascular endothelial growth factor (VEGF) and Granulocyte-colony stimulating factor (G-CSF) were lowered to naïve levels." (PMID 29330447, 2018). "The increased presence of adipocytes largely changes the hematopoietic stem cell niche in the BM microenvironment and sets up a niche for tumor cells, increasing their proliferation by IL-6 and Janus Kinase 2 (JAK2)." (PMID 30483273, 2018). "Theoretically, direct measurement of serum IL-6 levels is the optimal method to estimate SIR resulting from interactions between the tumor and the host tissue." (PMID 28744596, 2018). "IL-6 was considered to stimulate inflammatory cytokine production, tumor angiogenesis, and the tumor macrophage infiltrate as well as inhibit the differentiation of localized T cells to effector cells." (PMID 29293510, 2018). "The work with mouse organoids also strengthened available evidence that fibroblasts contribute to tumor survival and growth, probably through paracrine cytokines such as IL-6." (PMID 29587663, 2018). "IL-6 binds to its receptor on tumor cells and activates Janus kinase/signal transducer and activator of transcription (JAK/STAT) pathway." (PMID 30167088, 2018). "Ectopic expression of IL-6 is correlated with tumor progression and overall survival in patients with NSCLC." (PMID 29970138, 2018). "The expression of IL-6 mRNA decreased in our experiment, leading to an inhibition of proliferation and increase in apoptosis of tumor cells." (PMID 30564277, 2018).
tumor (continued). "These evaluations also showed that the presence of tumours in WT mice provoked a slight but significant decrease in Cd3g, Il6 and Il12a expression in this immune organ." (PMID 30166561, 2018). "In turn, IL-6 increases the expression of Jagged1 and Notch3 in tumor cells and stimulates tumor growth and drug resistance." (PMID 30154786, 2018). "IL-6 is recognized for stimulating tumor growth in GBM patients, whereas IL-10 is known for inhibiting IFN-γ and TNF-α production." (PMID 29651429, 2018). "Our work reveals that EC-derived IL-6 is critical for tumor growth and progression in a genetically induced GBM mouse model." (PMID 29422647, 2018). "Here, we show that pre-interventional serum levels of IL-6 and IL-8 not only predict patients’ local tumor response after TACE but are also indicative of the patients’ overall survival (OS)." (PMID 29899223, 2018). "Alpha-fetoprotein and IL-6 were compared in subgroups and the effectiveness of these markers was investigated in subgroup 1 (small-sized tumor)." (PMID 29963457, 2018). "Here, the authors show that in breast cancer models an IL-6 driven co-expression of FAP and HO-1 in tumour-associated macrophages, similar to the wound healing response, facilitates migration and metastatic spread." (PMID 30054470, 2018). "By understanding the disease progression at an organism level, we find that IL6, in addition to mediating the tumoral treatment resistance, also plays a central role in governing tumour–host interactions to promote disease progression." (PMID 29540470, 2018). "Inflammation induced through microbial or danger signals affects all stages of tumor development and the pro-inflammatory cytokines, IL-1β and IL-6, are important mediators for inflammation-induced tumorigenesis." (PMID 30447690, 2018). "In HCC, IL-6 promotes multiple stages of tumor development including initial hepatocyte proliferation, the transformation of hepatocytes into HCC progenitor cells (HcPCs), and the progression to HCC nodules and metastases." (PMID 29899223, 2018). "Our immediate goal is to quantify the influence of IL-6 on cancer stem cell self-renewal and survival, and to characterize the subsequent impact on tumor growth dynamics." (PMID 29351275, 2018). "Interleukin-6 (IL-6) is a pro-inflammatory cytokine that has been described as being involved in many tumorigenesis processes, particularly angiogenesis, tumor cell migration and invasion and cell growth and proliferation." (PMID 29951282, 2018). "Several lines of evidence indicate that the NF-κB and JAK/STAT3 pathways mediate the expression of inflammatory cytokines, such as IL-6, that flame the tumor microenvironment." (PMID 29707119, 2018). "Among them, IL-6 is one of the major immunoregulatory cytokines with a role in tumor proliferation, invasion, angiogenesis and chemoresistance." (PMID 29930760, 2018). "Previous studies suggest IL-6 to be a major regulator of tumor-stroma interaction in cancer microenvironment." (PMID 29898759, 2018). "Jagged1 activates stromal Notch signaling which in turn induces IL-6 secretion from osteoblasts stimulating tumor growth." (PMID 30515368, 2018). "IL-6 stimulates tumor cell proliferation and survival by activating the PI3K/AkT and JAK/STAT pathways via gp130 tyrosine phosphorylation." (PMID 29930760, 2018). "The cytokine/chemokine profiling underscores the role of IL-6 as a proinflammatory cytokine secreted by myeloid cells, T cells as well as tumor cells upon inflammatory signals and as a result of therapeutic treatments such as CMT." (PMID 29541413, 2018). "In summary, all these data suggest that ERβ/IL6 expression is significantly higher in metastatic lymph nodes than in primary NSCLC tumor tissue." (PMID 29970138, 2018). "These tumor cells perpetuate IL6 production, creating a positive feedback loop of increased IL6 and increased cell (normal and cancerous) proliferation." (PMID 30087267, 2018).
tumor (continued). "We have previously shown that the MAPK activated protein kinase 2 (MK2) pathway is responsible for the majority of IL-1β, IL-6, and TNF-α production in both a colitis-associated cancer and a tumor transfer model of CRC." (PMID 30298062, 2018). "Specifically, the secretion of the pro-inflammatory cytokine IL-6 from immune cells, promotes the invasiveness of tumor cells in an in vitro co-culture model of CRC." (PMID 29419779, 2018). "In previous studies, treatment with CT-26 CM suppressed myoblast proliferation and differentiation into myotubes and accelerated myotube degradation, suggesting that tumor-derived factors such as myostatin and IL-6 promote skeletal muscle wasting." (PMID 29662645, 2018). "Potential targets are generally tumor-promoting factors present in the TME such as IL-6, TGF-β, Gal-1, and Gal-3." (PMID 29682521, 2018). "Alternatively, myeloid-derived suppressor cells (MDSC) utilize IL-6 to support tumor progression through production of TGF-β1." (PMID 30444930, 2018). "A recent paper demonstrated that CAFs associated to incipient neoplasia exhibit a pro-inflammatory signature, leading them to mainly overexpress SDF-1, IL-6, and IL-1β, as well as to recruit proangiogenic macrophages." (PMID 30380628, 2018). "Tumor cells secrete a number of soluble molecules, including interleukin-6 (IL-6) and tumor necrosis factor-α (TNF-α)." (PMID 29887927, 2018). "Clinical studies showed that the overexpression of IL-6 and Cox-2 contributes significantly to tumor growth and blockades of IL-6 and Cox-2 signaling are potential chemotherapies." (PMID 30154906, 2018). "Tumour‐induced IL6 has been previously shown to mediate cachexia and treatment response in other cancer models." (PMID 29540470, 2018). "IL-6 and IL-10 in ascites promote the differentiation of macrophages into the immunosuppressive M2 phenotype, which stimulates tumor cell proliferation and suppresses the effector functions of cytotoxic T cells." (PMID 30687337, 2018). "Inflammation is an important component of the tumor milieu and of the premetastatic niche, in which IL-6 is an important player." (PMID 30246033, 2018). "Alpha-fetoprotein and IL-6 levels were compared in subgroups and effectiveness of these markers in subgroup 1 (tumor with small diameter) was investigated." (PMID 29963457, 2018). "Such a finding confirms the importance of IL-6 as an “exercise factor” with the ability to modulate the immune system during tumor progression." (PMID 30319436, 2018). "This implies that the 12% fractional occupancies predicted by our model leaves room for increases in proportion of bound IL-6R and more aggressive tumor growth when endothelial cells add to the amount of IL-6 available in the tumor microenvironment." (PMID 29351275, 2018). "Downstream effectors NF-κB, AP-1, STAT control the inflammatory milieu either by affecting tumor survival, growth, and tumor progression by signaling for molecules such as IL-6, IL-23 or by anti-tumor immunity (IFN-γ, IL-12)." (PMID 29696001, 2018). "Here, in this study, we have found AIRE as a host transcription factor which promotes tumor by acting as a transcriptional inducer of the IL-6 gene." (PMID 29795364, 2018). "In this study, we show that local tumor cell density in 3D collagen I matrices regulates the expression and activity of MMPs through the synergistic paracrine signaling mechanism between IL-6 and IL-8 via the JAK2/STAT3 pathway." (PMID 30220965, 2018). "Systemic administration of TNFα can lead to hypotension and hepatotoxicity while IL-6 is known to be present in the tumor microenvironment, where it supports the survival and proliferation of cancer cells." (PMID 29632539, 2018). "Herein, we report that AAM with high‐grade cancer have significantly higher IL‐6 expression in the tumor microenvironment." (PMID 29741809, 2018). "Tumor cells with high endogenous IL6 were more resistant to drug treatment than those with lower endogenous IL617." (PMID 30154433, 2018).
tumor (continued). "Correspondingly, IL-6 is regarded as an important tumour promoting factor in various types of human cancer including glioma, lymphoma, melanoma, as well as breast, ovarian, pancreatic, prostate, renal, and colorectal cancer." (PMID 30558287, 2018). "Literature data demonstrate that IL-6 is one of the major immunoregulatory cytokines present in the tumor microenvironment and found overexpressed in almost all types of tumor." (PMID 29930760, 2018). "This study presents role of IL-6/IL-6R-MAO-A signalling axis in invasion/angiogenesis in hypoxic tumour environment and highlights this signalling as critical target for cancer therapy." (PMID 29695771, 2018). "Matched samples of metastatic lymph node and primary tumor tissues were used to quantify the expression of ERβ/IL6 by western blot." (PMID 29970138, 2018). "Pro-inflammatory cytokines (e.g., TNF-α and IL-6) produced by tumor or host tissue due to tumor presence leads to both systemic and local inflammation in cancer." (PMID 29338749, 2018). "Many carcinomas have been found to express high levels of IL-6 and/or IL-8, suggesting an important role of these cytokines in the tumor microenvironment." (PMID 29416610, 2018). "This was correlated with a higher production of pro-inflammatory TNF-α, IL-1β, and IL-6 cytokines and a stronger stimulatory effect on tumor growth achieved by these activated macrophages as compared with controls." (PMID 29435437, 2018). "A different subset of CAFs, expressing low levels of αSMA but high levels of IL-6 was found at the periphery of the tumor and was termed the inflammatory CAF subset (iCAFs)." (PMID 30356656, 2018). "Paraneoplastic thrombocytosis is a known phenomenon in which inflammatory cytokines, such as interleukin-6 (IL-6), released by malignant cells lead to increased synthesis of thrombopoietin and platelet number, which in turn further stimulate tumor growth." (PMID 30333973, 2018). "We have developed a mathematical model for cancer stem cell-driven tumor growth that is designed to quantify the influence of tumor cell-secreted IL-6 signaling on tumor growth, cellular composition, and targeted therapy." (PMID 29351275, 2018). "Fibroblasts found in association with HL cells (so-called HL-AF for HL-activated fibroblasts) release growth factors and cytokines, such as TGF-β or IL-6 into the surrounding malignant tissue to support tumor growth and maintenance." (PMID 29967610, 2018). "Exercise was shown to induce the secretion of interleukin-6 from muscles and elicit anti-tumor immunity in combination with epinephrine by redistributing natural killer cells to tumor microenvironments." (PMID 30275370, 2018). "There is evidence that IL-6 is also expressed by macrophages found in the tumor microenvironment, especially by alternatively polarized macrophages." (PMID 29867925, 2018). "NF-κB, in turn, is known to induce TNFα, IL-1, IL-6 and IL-8 and thereby contributing to tumor cell growth an proliferation." (PMID 29930291, 2018). "Specifically, the authors showed that miR-22 decreased the production of IL-6, which in turn, inhibited the polarization of Th17 and the expression of IL-17A, finally promoting tumor growth." (PMID 30443251, 2018). "IL-6 has various context-dependent functions and has been shown to promote anti-tumor immunity through recruitment and stimulation of T cells." (PMID 29618376, 2018). "It is now known that skeletal muscles of cachectic mice are subjected to damaging stimuli due to the circulating cytokines produced by tumor and host-defense, in particular TNFα, INFγ and IL6." (PMID 30072615, 2018).